Y_RNA (Y RNA )
Gene: Miscellaneous RNA gene on chromosome 15 (99,681,786 to 99,681,877, reverse strand). Ensembl gene ENSG00000201724.
Homologues: Orthologues: chimpanzee Y_RNA (98% identical), macaque Y_RNA (91% identical), guinea pig Y_RNA (77% identical), guinea pig Y_RNA (70% identical), zebrafish Y_RNA (63% identical), guinea pig Y_RNA (62% identical), guinea pig Y_RNA (61% identical), guinea pig Y_RNA (60% identical), guinea pig Y_RNA (58% identical). Paralogues in human: RNY1 (80% identical), Y_RNA (80% identical), RNY1P11 (79% identical), Y_RNA (79% identical), Y_RNA (78% identical), RNY1P12 (77% identical), RNY1P7 (77% identical), Y_RNA (77% identical), RNY1P8 (76% identical), Y_RNA (76% identical), RNY1P5 (75% identical), Y_RNA (75% identical), and 85 more.